MIR96 (microRNA 96)
Synonyms: hsa-mir-96; DFNA50; MIRN96; miR-96; miRNA96
Gene: MicroRNA gene on chromosome 7 (129,774,692 to 129,774,769, reverse strand). Ensembl gene ENSG00000199158.
Gene Ontology:
Biological process: miRNA-mediated post-transcriptional gene silencing
Cellular component: RISC complex
Gene-disease validity (ClinGen):
ClinGen rates the evidence that MIR96 causes each of these diseases.
nonsyndromic genetic hearing loss (autosomal dominant): Moderate. A disease characterized by hearing loss that is not part of a larger syndrome.
Homologues: Orthologues: chimpanzee ptr-mir-96 (100% identical), dog MIR96 (100% identical), macaque mml-mir-96 (100% identical), rabbit MIR96 (100% identical), guinea pig MIR96 (99% identical), mouse Mir96 (97% identical), pig ssc-mir-96 (97% identical), zebrafish dre-mir-96 (81% identical), tropical clawed frog xtr-mir-96 (78% identical).
Diseases named in the same sentence as MIR96 in open-access papers:
MIR96 is named in the same sentence as 6 diseases in open-access papers, as found by Europe PMC text mining. Sharing a sentence is not in itself a finding about the gene and the disease. The quoted sentences say what the papers report.
hearing loss (8 papers, 2013 to 2024). "Examples of such genetic diseases include hearing loss associated with MIR96 mutations, eye disorders linked to MIR184 mutations, and skeletal dysplasia involving MIR140 mutations." (PMID 39457367, 2024). "Germline mutations in Mir96, one of three co-expressed polycistronic miRNA genes (Mir96, Mir182, Mir183), cause hereditary hearing loss in humans and mice." (PMID 29476110, 2018). "MIR96 was the first miRNA locus to be associated with a hereditary human disease when it was linked to the DFNA50 locus in two families with dominant non-syndromic progressive hearing loss." (PMID 24013374, 2013). "Prevention of hearing loss by CRISPR correction of the Mir96+14C>A mutation has recently been demonstrated to be effective in mice, but in vivo gene editing to treat hearing impairment has yet to be implemented in humans and requires precise knowledge of the underlying genetic pathology." (PMID 39434156, 2024). "Mutations in MIR96 are rare causes of deafness, but identifying novel variants like n.57T>C may shed light on the mechanisms underlying DFNA50-associated hearing loss." (PMID 39457367, 2024). "Family studies have led to the identification of many variants involved in adult-onset Mendelian hearing loss (for example, MIR96, DMXL2, reviewed in), but these tend to be very rare or even private variants, and are unlikely to explain all of the hearing loss seen in humans." (PMID 37163093, 2023). "We chose amitriptyline to test and found that it delays the progression of hearing impairment in Mir96+14C>A heterozygotes." (PMID 39434156, 2024). "Osbpl2 was among 132 mRNAs with 3′UTRs predicted to contain potential target sites for miR-96, a microRNA whose mutations cause progressive hearing loss in mice and humans, but we found no upregulation of Osbpl2 in Mir96 mutant mice (diminuendo)." (PMID 25759012, 2015). "Here, we performed editing by nonhomologous DNA end joining (NHEJ) to target a dominant Mir96 mutation (Mir96tm3.1Wtsi, referred to as Mir9614C>A in this report; equivalent of human rs587776523, g.7:129414596G>T in GRCh38) by AAV-mediated delivery in young adult mice with hearing loss." (PMID 38985856, 2024).
deafness (1 paper, 2024). An inherited or acquired condition characterized by the complete loss of the ability to hear from one or both ears. "While the Mir96+14C>A heterozygotes mimic the phenotype observed in the family with the equivalent mutation, the Mir96+13G>A heterozygotes escape deafness while the same mutation causes progressive hearing loss in humans." (PMID 39434156, 2024). "Auditory brainstem response (ABR) recordings showed that Mir96+13G>A and Mir96+14C>A homozygotes exhibit profound deafness at all ages tested, showing no response at the highest sound level tested (95 dB sound pressure level (SPL)) at any of the ages studied (14 days to 6 months old)." (PMID 39434156, 2024).
MIR96 also shares sentences with these, for which no sentence is quoted: genetic diseases (1 paper); Hearing impairment (1); skeletal dysplasia (1); tumours (1).